MROCKI (MARCKS cis regulating lncRNA promoter of cytokines and inflammation)
Synonyms: LOC285758; ROCKI; LINC01268
Gene: Long non-coding RNA gene on chromosome 6 (113,868,013 to 113,873,464, reverse strand). Ensembl gene ENSG00000227502.
Diseases named in the same sentence as MROCKI in open-access papers:
MROCKI is named in the same sentence as 3 diseases in open-access papers, as found by Europe PMC text mining. Sharing a sentence is not in itself a finding about the gene and the disease. The quoted sentences say what the papers report.
ovarian carcinoma (1 paper, 2023). A malignant neoplasm originating from the surface ovarian epithelium. "Both MROCKI and LNCAROD act as protective factors in ovarian cancer patients because higher expression of MROCKI and LNCAROD in tumor tissues are associated with the higher survival rate." (PMID 37597098, 2023). "Whereas the function of LNCAROD has been studied in other cancers, the function of MROCKI and AC096667.1 remains largely unknown, especially in pyroptosis and ovarian cancer." (PMID 37597098, 2023).
MROCKI also shares sentences with these, for which no sentence is quoted: cancer (3 papers); tumor (2).